PCNA (proliferating cell nuclear antigen)
Diseases named in the same sentence as PCNA in open-access papers (continued):
Sharing a sentence is not in itself a finding about the gene and the disease.
colon carcinoma (80 papers, 2007 to 2025). "NO-aspirin is nitric oxide-releasing synthase (NOS) along with two COX-2, as well as down-regulated expression of β-catenin and proliferating cell nuclear antigen (PCNA) in colon tumor, all these functions implicated in tumor formation inhibition." (PMID 32582499, 2020). "The colon cancer-associated markers proliferating cell nuclear antigen (PCNA) and COX2 were also difficult to detect in Lrrc19 KO mice." (PMID 26776522, 2016). "Colon cancer is frequently a pathological consequence of persistent oxidative stress, leading to DNA damage and mutations in cancer-related genes, cell cycle death and regeneration, where cellular overexpression of β-catenin and proliferating cell nuclear antigen (PCNA) are implicated." (PMID 20525330, 2010). "We further observed notable increases in expression levels of PCNA, β-catenin, and MDM2 widely recognized as cell proliferation markers associated with colon cancer in the AOM/DSS-treated mice." (PMID 39893188, 2025). "In this context, it is also important to mention that among SCFAs, only butyrate reduces the invasion of primary human colon cancer cells by reducing PCNA expression." (PMID 39859117, 2025). "The PCNA protein level decreased with increased lobeline concentration in mice tumors, indicating that lobeline inhibited the proliferation of colon cancer cells in a dose‐dependent manner." (PMID 39840525, 2025). "The same study, among others, was conducted on an in vitro model using human adenocarcinoma cells and measuring proliferating cell nuclear antigen (PCNA) in human colon cancer cell lines (COLO 320 DM)." (PMID 38794127, 2024). "Experiments on mice with AOM- and DSS-induced CAC and the mouse colon cancer cell line CT26 also demonstrated that PCNA expression is increased in tumor cells." (PMID 39063041, 2024). "Due to a direct relationship to cell proliferation, PCNA expression is a vital prognosis factor in colon carcinoma, which can be utilized as a marker of disease progression since it is related to high-grade dysplasia and increased colonic tissue size." (PMID 37375942, 2023). "UBE2I contributes to SUMOyation of PCNA and is a proposed therapeutic target in colon cancer and the SUMO conjugating activity of UBE2I also contributes to DNA repair." (PMID 36293188, 2022). "The effect of oral pterostilbene as an anti-promotion in our study can be supported by the previous study, as dietary intake of pterostilbene significantly reduced the expression of PCNA in azoxymethane-induced colon cancer in rats." (PMID 36359262, 2022). "Collectively, L. plantarum-12 oral administration promoted colonic tumor cells death via inhibiting PCNA and increasing pro-apoptotic Bax protein expression." (PMID 35565884, 2022). "In colon cancer, β-sitosterol decreases the expression of proliferating cell nuclear antigen (PCNA)." (PMID 36313365, 2022). "In colon cancer, β-sitosterol decreases the expression of proliferating cell nuclear antigen (PCNA), which is known as an indicator of cells’ proliferative activity." (PMID 34679718, 2021). "The RAD5 ortholog HLTF, important in PCNA polyubiquitination, is downregulated through promoter methylation in colon cancer cell lines and in primary tumors." (PMID 35198436, 2021). "Compared to WT group, colon tumors derived from Rnf6 tg mice exhibited higher Ki-67 and PCNA scores, consistent with the pro-tumorigenic effect of RNF6." (PMID 34611311, 2021). "C11 and G8, two inhibitors of the protein kinase AKT, inhibit damage-induced PCNA monoubiquitination and show synthetic lethality with UV-irradiation in BRCA1-deficient triple-negative breast cancer and colon cancer cell lines." (PMID 35198436, 2021). "The results suggested that LPEPS oral administration promoted colon tumor apoptosis of the AOM/DSS-treated colon cancer mice through down-regulating PCNA and activating caspase cascade." (PMID 34945611, 2021).
colon carcinoma (continued). "Lycopene in vivo was able to decrease the level of proliferating cell nuclear antigen (PCNA) and β-catenin, while an increase in p21 and E-cadherin adhesion molecule expression in colon cancer were noticed." (PMID 34948455, 2021). "Doxycycline has also been shown to inhibit cell proliferation in a human colon cancer cell line, which is consistent with the reduced PCNA expression observed in dox-treated shLuc mice after DSS treatment." (PMID 33673239, 2021). "Knockdown of lncRNA BC200 attenuates HCT-116 and HT29 colon cancer cell proliferation via downregulation of pSTAT3, Ki-67 and PCNA." (PMID 33246471, 2020). "Mechanistically, FAL1 interacts with STAT3 and triggers its phosphorylation to modulate the expression of Bcl-2, TGF-β1, p65, and PCNA in colon cancer cells." (PMID 33246471, 2020). "Among these proteins, AE1 is thought to be present in gastric and colon cancer cells; while PCNA, MCM6, α/β/γ-actin and α/β-tubulin, among others, have been observed in a lymphoblastoid cell line." (PMID 32204550, 2020). "This p21 peptide was fused with penetratin inhibited both cell proliferation and cell cycle progression in human colon cancer cells by two independent mechanisms involving cyclin-Cdk and PCNA." (PMID 28320393, 2017). "DFMO and Rosuvastatin low dose combination reduced PCNA a proliferation marker in treated colon tumors compared to untreated control colon tumors." (PMID 27841323, 2016). "Sulindac sulfide had been known to inhibit the proliferation of colon cancer cells and diminished expression of the proliferation markers PCNA and Ki-67." (PMID 27281609, 2016). "In DMH-induced colon tumor tissues PCNA was strongly expressed, particularly in the STZ + DMH group." (PMID 26376762, 2015). "In immunohistochemical analysis, the Ctr mice exhibited global and strong positive staining for PCNA and Ki67 in colon tumor cell nuclei." (PMID 26496833, 2015). "Our results showed that PCNA was expressed in DMH-induced colon cancer cells, and the strongest proliferation activity was observed in the DMH+STZ group." (PMID 25329503, 2014). "Lycopene inhibits in the progression of colon cancer in vivo by decreasing proliferating cell nuclear antigen (PCNA), increasing p21 and the activation of caspase 3, increasing the E-cadherin adhesion molecule, and decreasing nuclear levels of β-catenin." (PMID 23970935, 2013). "β-sitosterol induced significant dose-dependent growth inhibition of COLO 320 DM cells (IC50 266.2 μM), induced apoptosis by scavenging reactive oxygen species, and suppressed the expression of β-catenin and PCNA antigens in human colon cancer cells." (PMID 20525330, 2010). "In conclusion, our study indicates that silencing KCNQ1OT1 in HCT116 and SW480 cells may suppress colon cancer progression by negatively regulating DNA replication and the mitotic cell cycle phase-related pathways, targeting the downstream PCNA and CCNE2." (PMID 38361755, 2024). "In the subsequent in vitro experiments, after LEMD1 was depleted, the proliferation of colon cancer cells was observably impeded, as accompanied with the declined protein levels of proliferation markers Ki-67 and PCNA and invasion- and migration-related factors MMP2 and MMP9." (PMID 35294319, 2022). "Furthermore, the expression of proliferating cell nuclear antigen (PCNA) was reduced in colon tumors from pterostilbene-fed animals." (PMID 35056682, 2022). "Similarly, Angelica sinensis root extract administration was reported to depress colonic PCNA expression in the initial colon cancer stage of AOM/DSS-treated mice." (PMID 35565884, 2022).
colon carcinoma (continued). "We further texted whether the change in POU2F1 expression could modulate the H2O2-induced γ-H2AX and PCNA expression in colon cancer cells." (PMID 34997215, 2022). "In addition, our in vitro experiments demonstrated that HMGB1 induced proliferation and PCNA expression in CT26 colon cancer cells through the ERK1/2 pathway." (PMID 33160389, 2020). "Notably, FAL1 promotes cell invasion in part via modulation of Bcl-2, TGF-β1, p65, and PCNA expression in colon cancer cells." (PMID 33246471, 2020). "Nitric oxide (NO)-aspirin, a nitric oxide releasing prodrug of aspirin, inhibits the catalytic activity of nitric oxide synthase (NOS)-2, along with two COX-2, as well as down regulated expression of β-catenin and proliferating cell nuclear antigen (PCNA) in colon tumors induced by azoxymethane." (PMID 30096840, 2018). "The PTX treatment decreased the incidence of colon cancer and the rate of occurrence of PCNA-positive intestinal epithelial cells compared to those in control rats, indicating that PTX suppressed colon tumorigenesis and intestinal epithelial cell proliferation." (PMID 30338039, 2018). "β-sitosterol is a component of beans that has been shown to inhibit growth of COLO 320 DM cells (IC50 266.2 μM), by scavenging reactive oxygen species and inducing apoptosis; as well as suppressing the expression of β-catenin and PCNA antigens in human colon cancer cells." (PMID 30583518, 2018). "β-sitosterol, a phytosterol found in OO, inhibited significantly the growth of COLO 320 DM cells, in a dose-dependent way, caused apoptosis by scavenging ROS, and suppressed the expression of beta-catenin and proliferating cell nuclear antigen (PCNA) in human colon cancer cells." (PMID 30583613, 2018). "Rat colon tumors exposed to sulindac and naproxen individually or in combination with atorvastatin showed significant suppression of PCNA, cyclin D1 and β-catenin and reduced key inflammatory markers, inducible NOS and COX-2, p65, as well as inflammatory cytokines, TNF-α, IL-1β, and IL-4." (PMID 30096840, 2018). "In contrast, the colon tumors of the Atg5-deficient mice exhibited partial negative staining for PCNA and Ki67." (PMID 26496833, 2015). "Of note, PCNA forms a complex with Hsp90 in HCT-116 (human colon cancer cell line), HT-29 (human colorectal adenocarcinoma), and in HNSCC-1483 (human head and neck cancer cell line), the treatment with geldanamycin resulting in the degradation of both PCNA and Hsp90." (PMID 26501335, 2015). "PCNA was strongly expressed in DMH-induced colon tumor cells, especially in the DMH+STZ group." (PMID 25329503, 2014). "PCNA correlates with the proliferation of cells in many human tumors, including colon cancer." (PMID 23554613, 2010). "Hence from both our in vitro and in vivo results it is evident that β-sitosterol exhibits chemopreventive potential in DMH induced experimental carcinogenesis by inhibiting levels of β-catenin and PCNA accumulation in colon cancer." (PMID 20525330, 2010). "The ability to induce apoptosis was determined by its in vitro antiradical activity, cytotoxic studies using human colon adenocarcinoma and normal monkey kidney cell lines, and the expression of β-catenin and proliferating cell nuclear antigen (PCNA) in human colon cancer cell lines (COLO 320 DM)." (PMID 20525330, 2010). "However, in tumour studies Klotho has been shown to have antiproliferative effects, decreasing PCNA expression in colon cancer cells, and we hypothesise it may be protective during the acute phase of IRI." (PMID 28129785, 2017).
colon carcinoma (continued). "This study revealed that remimazolam promoted the cell-cycle progression and proliferation of HCT8 colon cancer cells by upregulating CDK1, PTTG1, CDC25C, CDK4, PLK1, PCNA, Ki67, RNASEH2B, FEN1, Cyclin D1,CD44 CDK2, CDKN3, CDC45, IQGAP3, and CDK6." (PMID 38725628, 2024). "The reduced number of colonic tumors in the ID + AOM/DSS and IOL + AOM/DSS groups was accompanied by the downregulated expression of cell proliferation regulators (PCNA, cyclin D1, and c-Myc)." (PMID 35631174, 2022). "elucidated that SIT triggers dose-dependent growth inhibition of human colon cancer COLO 320D cells by scavenging ROS, inducing apoptosis, and inhibiting the expression of β-catenin and PCNA antigens in human colon cancer cells." (PMID 35756648, 2022). "In a rodent model of azoxymethane (AOM)-induced colon cancer, the intake of PTS (40 ppm) through the diet for 45 weeks led to a reduction in tumorigenesis and diminished the levels of proliferating cell nuclear antigen (PCNA), cyclin D1, and β-catenin." (PMID 36234852, 2022). "This strategy was sufficient to diminish the number of colon tumors and was concomitant with reduction of inflammatory cytokines, IGF-1, and cell proliferation, the latter assessed via immunohistochemistry for proliferating cell nuclear antigen (PCNA)." (PMID 31906264, 2020). "The ability of MPE to inhibit cell growth was also confirmed using western blotting analysis of the proliferating cell nuclear antigen (PCNA), a well-known marker of cell proliferation whose level was decreased by MPE treatment in all colon cancer cells." (PMID 31546694, 2019). "Comparable results for PCNA (exception: OXA) and Ki-67 gene expression were obtained in SW480 and SW620 colon cancer cells." (PMID 29403306, 2017). "Overall, PCNA protein expression in Rosuvastatin and DFMO treatment groups and low dose combination groups showed a significant decrease compared to untreated colon tumors (p < 0.002)." (PMID 27841323, 2016). "Treatment of colon cancer cell lines with 5-FU induced ATF3 along with other DNA damage response genes (GADD34, GADD45α, PCNA)." (PMID 20137089, 2010). "DLD1 p21PCNA− human colon carcinoma cell lines expressing a mutant form of p21, which interfered with its interaction with PCNA, were not able to arrest at the G2/M checkpoint." (PMID 31112565, 2019). "They reported that an overexpression of periplakin reduced cancer cell migration and invasion, induced a G1/G0 cell cycle arrest, and inhibited colon cancer cell proliferation by suppressing the activation of ERK1/2 and the expression of proliferating cell nuclear antigen (PCNA)." (PMID 29587367, 2018). "The results obtained in the present study shown that the expression of PCNA in all DMH-induced tumor tissues were higher when compared with the normal tissue and that MET treatment apparently inhibited the proliferation of colon cancer cells when compared with the STZ + DMH group." (PMID 26376762, 2015). "PPARγ increased in most cancer specimens versus mucosa, with a decrease in c-Myc and in PCNA proteins, suggesting that colon cancer growth is due to increased cell survival rather than increased proliferation." (PMID 17389773, 2007). "Furthermore, the protein levels of PCNA protein (a marker for cell proliferation), cyclin D1 and cyclin E (key regulators of the cell cycle), and MMP-9 (a key regulator of metastasis in colon cancer), as well as TNFα (a marker for extrinsic cell apoptosis) in nude mice were measured by IHC." (PMID 36979011, 2023). "Together with the unchanged levels of the colon cancer stem markers NANOG, SLUG and SNAIL, these effects suggest that the increased trend in cell proliferation usually associated with Ki67 and PCNA is not characterized by phenotypic traits suggesting cancer progression, at least in this cell model." (PMID 34987311, 2021).
colon carcinoma (continued). "BEND5 overexpression in DLD-1 colon cancer cells and BEND5 knockdown in COLO 320 DM colon cancer cells indicated that BEND5 could significantly change their expression levels, suggesting that BEND5 may directly or indirectly regulate CCNB1, PCNA and BCL2." (PMID 29371920, 2017). "In addition, ATX was shown to impede proliferation in a hamster model of oral cancer by regulating the expression of cyclin D1 and proliferating cell nuclear antigen (PCNA) and decrease cell viability in human HCT-116 colon cancer cells in dose- and time-dependent manners." (PMID 26184238, 2015). "Although PCNA+ epithelial cells were barely detected in the control, PCNA expression was markedly increased in the nuclei of tumor cells after AOM and DSS treatment, suggesting that excessive proliferation of tumor cells ultimately led to the development of colon cancer." (PMID 23272179, 2012). "A non-significant decrease in PCNA with individual low doses was observed in colon tumors of animals fed DFMO and Rosuvastatin, compared to the colon tumors of control fed animals." (PMID 27841323, 2016).